FGF2 (fibroblast growth factor 2)
Diseases named in the same sentence as FGF2 in open-access papers (continued):
Sharing a sentence is not in itself a finding about the gene and the disease.
cancer (continued). "Activation of VEGF/VEGFR signaling in IM-resistant GIST cells might be a result of FGF2 production by KIT-inhibited cancer cells, which in turn leads to the production and secretion of VEGF-A, and thereby activates VEGFR-mediated cascade." (PMID 39272961, 2024). "Moreover, the plasmatic concentration of FGF-2 is increased in many cancers, such as leukemia, lung and breast cancer, often in a metastatic state." (PMID 38672507, 2024). "However, during pathological conditions such as cancer, FGF2 is reported to interact with FGFR3 to promote angiogenesis." (PMID 39766329, 2024). "Using public databases in GEO and TCGA, we found that the mRNA expression level of KLF5 positively correlated with that of FGF-BP1, which could bind to fibroblast growth factors such as FGF2, thus promoting the progression of cancer disease, including ESCC." (PMID 38087142, 2023). "COX-2 stimulates the cancer cells to secrete angiogenic factors, including FGF-2 and VEGF-A." (PMID 36672505, 2023). "Moreover, there was an increased expression of genes responsible for the extracellular matrix organization and cancer cell invasiveness, including collagen, laminins, and FGF2 activation, in response to CBD and cisplatin." (PMID 37834191, 2023). "Cancer cells release growth factors, such as FGF-2, VEGF, PDGF, EGF, TGFβ, and cytokines and chemokines, the core group consisting of CCL2, CCL5, IL-6, IL-8, as well as other soluble factors that activate fibroblasts and modulate CAF gene expression patterns and their metabolism." (PMID 37046676, 2023). "Leptin, ferritin, FGF2, and prolactin may potentiate cancer stem cell formation; ferritin also impacts pathways leading to the EMT transition." (PMID 37857666, 2023). "Additionally, the increased levels of HIF1α and FGF2 indicated activation of survival pathways in cancer cells and possible stimulation of EMT, which would constitute unwanted effects of combinational treatment." (PMID 37834191, 2023). "Furthermore, this study aims to examine the chemotherapeutic efficacy of novel formulations as inhibitors of the Her2/neu pathway and their ability to target the FGFR2/FGF2 axis mechanisms and enhance the apoptotic activity in cancer cells." (PMID 38139837, 2023). "Thus, identifying the FGF-2 regulated gene networks in these contexts will help in devising FGF-2-based therapeutic approaches for cancer." (PMID 36038571, 2022). "In fact, FGF2 is supplemented in growth medium for ex vivo culture of cancer cells, including GBM." (PMID 36046049, 2022). "Thus, epithelial cells undergoing EMT and aggressive cancer cells become sensitive to FGF-2 and FGF-4, likely through upregulated FGFR1-IIIc expression." (PMID 36140527, 2022). "Our data highlights that the upregulation of PRSS23/FGF2 may be critical for macrophage infiltration in pan-cancer." (PMID 36189305, 2022). "In addition to growth factors of the VEGF family, many other mediators have been implicated in promoting lymphangiogenesis in cancer, including PDGF-BB, FGF2, and HGF." (PMID 35504887, 2022). "As expected, cancer cells showed significantly high FGF-2 expressions." (PMID 35439170, 2022). "In turn, CAFs produced high levels of fibroblast growth factor 2 (FGF2), initiating a signaling cascade in cancer cells that reduced retinoic acid-inducible gene I (RIG-I) expression and impeded the ability of malignant cells to detect and respond to OV infection." (PMID 36361831, 2022). "Since the higher expression of FGF-2 is linked to oncogenesis, we wanted to investigate whether the treatment of normal and cancer cells with FGF-2 will lead to increase in cell proliferation." (PMID 36038571, 2022). "In this investigation, we characterize the FGF-2 regulated transcriptome in immortalized human embryonic kidney cells HEK293 and cancer cell lines such as HeLa and BT-549 and identify common and uniquely enriched FGF-2 regulated biological pathways in normal and cancer cells." (PMID 36038571, 2022).
cancer (continued). "FGF2 is a vital mitogen that plays a key role in tissue homeostasis and cancer onset." (PMID 36505741, 2022). "In the field, FGF-2-induced AAD resistance has been described in other cancers." (PMID 35985991, 2022). "Therefore, blocking the biological functions of FGF2 by either limiting its secretion into the extracellular space or inhibiting FGF2 signaling into cells are suitable strategies in anti-cancer treatments." (PMID 35348113, 2022). "Of note, our work has uncovered FGF-2 induced sense and antisense transcripts IER3 and IER3-AS1, encoded from a convergent pair of genes, as crucial entities in FGF-2 dependent cancer associated biological pathways, such as pro-survival and chemokine regulated cell migratory behavior." (PMID 36038571, 2022). "FGF2 causes a significant reduction of IFN-γ, TNF-α and granzyme B production by in vitro stimulated CD8 T cells and decreased their efficiency in killing target cancer cells." (PMID 35479076, 2022). "On the other hand, in the FGF-2 treated HeLa cells, overrepresentation of cancer-associated pathways such as chemotaxis, angiogenesis, cell proliferation, inflammation and apoptotic pathways was observed, indicating different roles of FGF-2 in cancer and normal cells." (PMID 36038571, 2022). "Moreover, to reduce the ability of inhibiting autophagy, promoting proliferation and EMT by FGF2, and to inhibit the ability of promoting cancer cell metastasis by WNT7A, AKT1 was selected as a biomarker to be inhibited." (PMID 35743172, 2022). "IIIc is expressed preferentially in mesenchymal cells and promotes the migration and invasiveness of cells in response to FGF-2, in agreement with the observation that IIIb-to-IIIc switch is related to epithelial-mesenchymal transition and invasive phenotype of cancer cells." (PMID 34715919, 2021). "FGF2 was involved in cell growth, differentiation, and metastasis of cancers, including HCC." (PMID 34873170, 2021). "In addition, FP-1039 reduces plasma level of FGF2 in cancer patients in whom standard therapy has been ineffective." (PMID 34830951, 2021). "Moreover, AGO2 protein seems to be involved in the negative regulation of FGF2, which is elevated in numerous cancers and contributes to rapid proliferation of cancer cells." (PMID 33668654, 2021). "FGF2 has been heavily implicated as a proangiogenic factor, promoting endothelial proliferation and migration following FGFR1/2 signalling and VEGF/angiopoietin 2 secretion, and has been shown to mediate resistance to VEGFR targeted therapy in cancer." (PMID 34830836, 2021). "Additionally, circ_0018289 knockdown decreased the levels of angiogenesis inducers VEGFA and FGF2 in the two cancer cell lines." (PMID 34404391, 2021). "Based on its high efficiency and low toxicity, ds-Diabody against FGF-2 may provide an effective strategy for cancer therapy." (PMID 33718141, 2021). "Interestingly, it has also been demonstrated that secretion of FGF2 can lead to increased cancer cell adhesion and inhibition of invasion of cancer cells." (PMID 33918004, 2021). "Interestingly, FGF2 has been widely identified as an oncogene that participates in tumorigenesis and metastasis in multiple cancer types." (PMID 34271943, 2021). "Furthermore, increased levels of FGF2 were detected in the serum of cancer patients who have become resistant to VEGF-targeted therapy, which suggests the indirect role of FGF2 in angiogenic resistance." (PMID 33935756, 2021). "Additionally in pancreatic adenocarcinoma, CAFs secrete FGF2, which enhances cancer survival by increasing CXCL8 level." (PMID 34830951, 2021). "FGF2 plays a role in embryonic development, tissue homeostasis, wound healing, and cancer." (PMID 34067330, 2021). "The growth-inhibitory and cytotoxic effects of nanoparticle-mediated intracellular delivery of FGF-2 may be broadly applicable to cancer cells that derive from the lung, and perhaps from other tissues/organs." (PMID 32230722, 2020).
cancer (continued). "However, these cells maintain active the same VEGFA-activated pathways by the upregulation of others alternative TRK receptor ligands (i.e. FGF2, PDGFD and KITLG) that have been implicated in the development and drug resistance in other cancer types." (PMID 34316686, 2020). "FGF2 homeostasis is disrupted in several diseases including cancer and cardiovascular diseases." (PMID 32370284, 2020). "Again, FGF-2 expression neutralized the antitumor effect of imatinib in this cancer model." (PMID 32709869, 2020). "Moreover, the expression of FGF2-mRNA in the cancer tissues was significantly higher than that in the adjacent tissues in RT-PCR test, which was consistent with the results of IHC." (PMID 33381388, 2020). "Overall, the combination of FGF2 and proteasome or checkpoint inhibition increased the cell death and reduced the number of live cells to a greater extent than the respective stimuli as single agents in all four cancer cell models." (PMID 30422399, 2019). "Here, we tested whether FGF2 can selectively sensitize cancer cells to stress‐targeted therapeutic inhibitors." (PMID 30422399, 2019). "While this major question cannot be exhausted in the scope of this current work, the data provided here show that FGF2 can efficiently disturb the homeostasis of cancer cells from different origin and phenotypes, increasing the toxicity of checkpoint and proteasome inhibitors." (PMID 30422399, 2019). "In addition, it is known that FGF-2 secreted from astrocytes can stimulate cancer cell proliferation." (PMID 32038161, 2019). "Finally, we highlight FGF2 signalling as one of numerous components of the complex regulation of stemness in cancer." (PMID 31758153, 2019). "In one study involving the co-culture of colorectal cancer cells with CAFs expressing FGF-2, the phenotype of the cancer cells altered to become more elongated, they were able to migrate longer distances, and invaded into Matrigel supplemented with fibroblasts." (PMID 31861782, 2019). "In this regard, exogenous administration of the fibroblast growth factor 2 (FGF2) might be a viable alternative to overload cellular stress pathways in cancer cells." (PMID 30422399, 2019). "However, most of these results are based on established cancer models, in which an optimal FGF2 signaling level was selected during malignant progression and is now part of its adapted and robust phenotype." (PMID 30422399, 2019). "In the first cluster, 100% of pairs of cancer biomarkers (36/36) exhibited positive correlation (adjusted P < 0.05) with the highest correlations between FGF2 and leptin (ρ = 0.84, P < 0.0001), FGF2 and TRAIL (ρ = 0.80, P < 0.0001) and leptin and TRAIL (ρ = 0.77, P < 0.0001)." (PMID 31089160, 2019). "Therefore, it would be an effective strategy to explore FGF2 inhibitors from existing drugs to facilitate cancer treatment." (PMID 31035725, 2019). "We conclude that FGF2 undergoes 3’ UTR shortening in these cancers." (PMID 30005633, 2018). "Due to the diversified mode of action the dual warhead-FGF2 conjugate may overcome the potential acquired resistance of FGFR1-overproducing cancer cells towards single cytotoxic drugs." (PMID 30029518, 2018). "We have recently demonstrated that FGF2, a natural ligand of fibroblast growth factor receptors (FGFRs), can be used as an alternative to antibodies for the selective and efficient delivery of cytotoxic drugs into cancer cells overproducing FGFRs." (PMID 30029518, 2018). "FGF2 is a well-known mitogen of fibroblasts and cancer cells." (PMID 29861860, 2018). "Interestingly, miR-16 also suppresses the fibroblast growth factor-2 (FGF-2)/FGF receptor-1 (FGFR-1) axis, and therefore, the loss of this miRNA can eventually enhance cancer cell survival, proliferation, and migration." (PMID 29558956, 2018).
cancer (continued). "The secreted growth factors, such as transforming growth factor-β (TGF-β), platelet-derived growth factor (PDGF), and fibroblast growth factor-2 (FGF-2) released by cancer cells, play a key role in the activation of fibroblasts in DGC, and particularly in scirrhous GC." (PMID 30115886, 2018). "Remarkably, the expression of IL‐8, TGF‐β, VEGFA, VEGFR1, VEGFR2, and FGF2, which had been described as promoting cancer cell proliferation, is significantly reduced on 2‐FF‐treated cells, suggesting that the decreased growth factors are the underlying mechanism for the reduced cell proliferation." (PMID 29215790, 2018). "In summary, we propose the following mode of action for FGF2 dual warhead conjugate: The conjugate recognizes elevated levels of FGFR1 on the surface of cancer cells and utilizing receptor-mediated endocytosis it is targeted into lysosomes, degraded releasing α-amanitin and MMAE." (PMID 30029518, 2018). "We didn’t observe any cytotoxic effect of single conjugates towards NCI-H446 cells, while FGF2 dual warhead conjugate killed almost 95% of cancer cells, demonstrating that dual conjugation strategy may help in combating cancer resistance." (PMID 30029518, 2018). "FGF2 is produced by different cell types (including endothelial cells, immune cells, fibroblasts, and cancer cells) and plays pleiotropic roles in different settings, including inflammation, tissue remodeling, wound repair and cancer." (PMID 30443492, 2018). "Besides, as FGF2 is an in vivo modulator of matrix metallopeptidase 13 (MMP-13) expression in malignant tumors, a significant decrease in the level of MMP-13 protein was also observed in miR-195 overexpressing cells." (PMID 28740507, 2017). "Interestingly, activation of PERK induced FGF2 expression in independent model systems as shown in hypoxic muscle and in cancer cells following glucose deprivation, pointing towards a general regulatory mechanism." (PMID 29235576, 2017). "Quite interestingly, genes and associated interaction partners that were downregulated upon Hic-5 KD comprised members and/or associated partners of the TGFβ pathway (including TGF-β2, TGFβR, TGFβRII, FGF2, CTGF, FGFR, SRC, RUNX2 and CDH2), that are commonly implicated in inducing EMT in cancer." (PMID 29137281, 2017). "Indeed, prostate tumors express various FGF family members, including FGF2 and FGF8b, with paracrine/autocrine functions on cancer epithelial/stromal cells." (PMID 29137286, 2017). "High expression of FGF2 correlates with a worse survival for relapsed/refractory cancer patients." (PMID 27007053, 2016). "AGM-1470, miRNA 646, and interferon alpha downregulate FGF2 expression in cancer cells." (PMID 27007053, 2016). "In addition, high expression level of FGF-2 in cancer cells would be necessary for making msFGFR2c work since FGF-2 is required for the binding of msFGFR2c to the receptor in this study." (PMID 28049184, 2016). "Several studies have compared FGF2 serum levels in cancer patients to those in healthy volunteers." (PMID 27007053, 2016). "The differential expression and localization of FGF2 was also studied in different cancers." (PMID 27007053, 2016). "Indeed, pre-clinical and clinical studies have shown that progressive disease in VEGF inhibitor-treated cancer can be mediated by FGF2 and SDF-1α; two of the multiple angiogenic cytokines that are critically dependent on heparan sulfate (HS)." (PMID 27490176, 2016). "Therefore, msFGFR2c has a potential application for the treatment of FGF-2- and FGFR2c/FGFR1c-positive cancers." (PMID 28049184, 2016). "While cryopreservation of ovarian tissue followed by autotransplantation still is under investigation, combined VEGF and FGF2 might be the promising remedy to preserve fertility for children and young women with cancer." (PMID 27483256, 2016). "Other FGF2 antagonists are under investigation for cell line and animal preclinical cancer models." (PMID 27007053, 2016).
cancer (continued). "FGF2 is frequently dysregulated in cancer, especially in advanced stages of disease." (PMID 27007053, 2016). "In addition, fibroblasts that are abundant in the stroma of carcinomas at advanced stages of disease can mediate resistance to treatment via FGF2 secretion." (PMID 27007053, 2016). "Co-culture with cancer cells further enhanced fibroblasts FGF-2 mRNA expression by about 3 fold." (PMID 25973543, 2015). "Therefore, FGF2 and FGFRs have gained interest as promising targets for drug development in cancer therapy." (PMID 25609197, 2015). "Besides TGFβ1, the identification and functional verification of additional cancer or fibrosis-associated factors, EGF, FGF2 and PDGF-BB, further confirmed the functional relevance of the invasion signature." (PMID 26243655, 2015). "It has been reported that bFGF/FGF2 induces shedding of SDC1 in cancer cells." (PMID 26293675, 2015). "Strikingly, abrogation of nuclear FGFR1 and FGF2 in PSCs abolished cancer cell invasion." (PMID 24503018, 2014). "Consequently, normal epithelial cells that have undergone EMT as a result of combined TGF-β and FGF-2 stimulation promoted the invasion of cancer cells." (PMID 23715860, 2013). "Although targeting FGF2 signalling as a cancer therapy has been lagging behind that of other receptor tyrosine kinases, including epidermal growth factor (EGF) signalling, clinical reagents that specifically target the FGFs or FGF receptors are being developed and included in clinical trials." (PMID 22732006, 2012). "The authors proposed the 24 kDa FGF2 isoform as a new regulator of DNA repair in cancer cells." (PMID 22732006, 2012). "siRNA expression silencing confirmed that FGF-2 originates from the fibroblasts but it is unclear whether the growth factor acts on the carcinoma cells or modulates the fibroblasts in an autocrine manner." (PMID 23056402, 2012). "In conclusion, FGF2 appears to be an activator of DNA repair in carcinoma cells." (PMID 22732006, 2012). "In the present study, we propose that the fast repair in carcinoma stem cells could be mediated by the intracellular HMW isoforms of FGF2, in an intracrine manner." (PMID 22732006, 2012). "In light of these findings we hypothesize that TYK2 and other JAKs are important modulators of FGF-2-driven cell survival and that inhibitors of these kinases will likely improve the effectiveness of other cancer therapies." (PMID 21625473, 2011). "Collectively, our data suggest that TYK2, JAK1 and JAK2 are novel targets that may prove useful to circumvent drug resistance mediated by FGF-2, a growth factor often secreted by cancer cells, or their supporting tissues, and elevated in cancer patients." (PMID 21625473, 2011). "Furthermore, this suggests that the endothelial signalling pathways induced by FGF2 are context dependent, i.e. dependent on the nature of the external stimulus, such as cancer conditioned medium, from which the FGF2 originates." (PMID 20092633, 2010). "Moreover, FGF-2 performs an additional promotion of TGF-β driven EnMT or epithelial-mesenchymal transition (EMT) in a renal tubular epithelial cell or cancer cells." (PMID 19081766, 2008). "Inhibition of stromal PDGF receptors reduced proliferation and angiogenesis in cervical lesions through a mechanism involving suppression of expression of the angiogenic factor fibroblast growth factor 2 (FGF-2) and the epithelial cell growth factor FGF-7 by cancer-associated fibroblasts." (PMID 18232728, 2008). "Notably, human cervical neoplasias and carcinomas coexpressed FGF-2 and PDGF receptors in stromal cells, revealing a close similarity between this mouse model and the human disease." (PMID 18232728, 2008). "In the same way, FGF-2 can stimulate cancer cell proliferation and prevent cell death." (PMID 12838321, 2003). "Various regulators might be involved in FGF2 expression in different cancers." (PMID 39039912, 2024).